ETV4 (ETS variant transcription factor 4)
Description:
Transcriptional activator. Regulates the positioning of motor neurons within the lateral medial column of the spinal cord and controls the terminal arborization of specific motor neuron axons within their target muscles (By similarity). Required for the expression of CDH8 and SEMA3E in ETV4-expressing motor neurons and for the exclusion of CDH7 expression from these neurons (By similarity). May play a role in keratinocyte differentiation. (Microbial infection) Binds to the enhancer of the adenovirus E1A gene and acts as a transcriptional activator; the core-binding sequence is 5'-[AC]GGA[AT]GT-3'.
Synonyms: E1AF; PEA3; E1A-F; PEAS3
Tractability: PROTAC: UniProt records ubiquitination sites on it.
Gene: Protein-coding gene on chromosome 17 (43,527,842 to 43,579,620, reverse strand). Ensembl gene ENSG00000175832.
Subcellular location: Nucleus
Subcellular location (Human Protein Atlas): Nucleoli rim; Mitotic chromosome
Pathways (Reactome):
Signal Transduction: MAPK6/MAPK4 signaling
Gene Ontology:
Molecular function: DNA-binding transcription activator activity, RNA polymerase II-specific; protein binding; RNA polymerase II cis-regulatory region sequence-specific DNA binding; sequence-specific double-stranded DNA binding; DNA-binding transcription factor activity, RNA polymerase II-specific; DNA-binding transcription factor activity; sequence-specific DNA binding
Biological process: positive regulation of keratinocyte differentiation; positive regulation of transcription by RNA polymerase II; cell differentiation; regulation of transcription by RNA polymerase II; regulation of DNA-templated transcription
Cellular component: nucleolus; chromatin; nucleoplasm; nucleus
Genetic constraint (gnomAD): Loss-of-function variants: 42 observed, 66.14 expected, observed/expected ratio (o/e) 0.63, 90% interval 0.5 to 0.82. The upper end of that interval is the gene's LOEUF score, 0.82, which puts it in group 3 of 6, group 1 being the genes least tolerant of losing a copy. Missense variants: 583 observed, 645.53 expected, observed/expected ratio (o/e) 0.9, 90% interval 0.84 to 0.97. Synonymous variants: 238 observed, 263.19 expected, observed/expected ratio (o/e) 0.9, 90% interval 0.81 to 1.01.
Homologues: Orthologues: chimpanzee ETV4 (99% identical), macaque ETV4 (99% identical), pig ETV4 (95% identical), dog ETV4 (94% identical), mouse Etv4 (93% identical), rat Etv4 (92% identical), guinea pig ETV4 (80% identical), rabbit ETV4 (75% identical), zebrafish etv4 (61% identical), tropical clawed frog etv4 (43% identical), Drosophila melanogaster Ets96B (34% identical). Paralogues in human: ETV1 (55% identical), ETV5 (52% identical), ETS1 (20% identical), ETS2 (20% identical), FLI1 (18% identical), ELF2 (17% identical), ERG (17% identical), GABPA (16% identical), ETV6 (15% identical), ELF1 (15% identical), ELF4 (15% identical), ETV2 (14% identical), and 16 more.
Diseases named in the same sentence as ETV4 in open-access papers:
ETV4 is named in the same sentence as 128 diseases in open-access papers, as found by Europe PMC text mining. Sharing a sentence is not in itself a finding about the gene and the disease. The quoted sentences say what the papers report.
breast cancer (61 papers, 2004 to 2025). A primary or metastatic malignant neoplasm involving the breast. "Previous studies have demonstrated that the loss of ETV4 significantly hampers the expression of glycolytic enzymes, diminishes glucose uptake, and reduces lactate release in breast cancer cells." (PMID 39389944, 2024). "Among the commonly regulated FGF1 genes was Ets variant transcription factor 4 (ETV4), which has been shown to influence ER DNA binding activity in endometrial cancer cells, and glycolytic gene expression in breast cancer cells." (PMID 37608351, 2023). "For example, the binding of ETS variant transcription factor 4 (ETV4) to the AP-1 binding site in the MMP-13 promoter region induced MMP-13 expression in breast cancer." (PMID 35805035, 2022). "ETS variant transcription factor 4 (ETV4) was also reported to be highly expressed in breast cancer and prostate cancer, which was associated with distant metastasis of prostate cancer through PI3-kinase and Ras signaling." (PMID 33708105, 2020). "Similarly, previous studies have linked ETV4 with shorter survival times in patients with breast cancer, pancreatic cancer, and colorectal cancer." (PMID 40469297, 2025). "Furthermore, ETV4 plays a crucial role in activating the Sonic Hedgehog signaling, which is associated with the maintenance of breast cancer stemness." (PMID 39389944, 2024). "Knockdown or overexpression of ETV4 significantly restrains or fosters breast cancer cell stem-like traits, and ETV4 loss suppresses the expression of stemness markers including c-MYC, OCT4, NANOG, LIN28, suggesting that ETV4 acts as a key regulator in BCSC maintenance." (PMID 34052833, 2021). "In breast cancer, ETV4 promotes metastasis by transcriptionally activating EMT inducers and extracellular matrix–degrading proteinases." (PMID 41154660, 2025). "In breast cancer, ETV4 and ETV5 are also involved in the maintenance of cancer stem cells and their self‐renewal via the regulation of sox2 or Sonic Hedgehog signalling." (PMID 40275610, 2025). "Numerous studies have shown that high expression of ETV4 in prostate cancer, breast cancer, colorectal cancer, pancreatic cancer, and cholangiocarcinoma often correlates with poor prognosis." (PMID 40777122, 2025). "In non-small cell lung cancer and breast cancer, ETV4 was found to promote the migration and metastasis by transactivating MMPs." (PMID 38849954, 2024). "Zhu et al23 presented that ETV4 facilitates breast cancer stemness via enhancing glycolytic activity." (PMID 37553792, 2023). "For comparison, canonical ETV4 transcripts are the most abundant also in breast cancer (66.2%) and leukemic (85.2%) cell lines." (PMID 37002241, 2023). "Tao Zhu and colleagues reported that ETV4 promotes breast cancer cell stemness by activating glycolysis and CXCR4-mediated sonic hedgehog signaling." (PMID 37205199, 2023). "It was reported that the aberrant expression of ETV4 plays a critical role in the pathogenesis of various malignancies, including breast cancer, lung cancer, endometrial cancer, gastric cancer, and HCC." (PMID 35121725, 2022). "The S100A9-MCAM axis activates ETS translocation variant 4 (ETV4), which in turn transcriptionally upregulates ZEB1 to induce epithelial-mesenchymal transition and metastasis of breast cancer cells." (PMID 35484101, 2022). "Our study highlights the potential of ETV4 as a promising target to simultaneously suppress glycolysis and cancer cell stemness in breast cancer." (PMID 34052833, 2021). "Targeting ETV4 represents a potential therapeutic approach to disrupt cell metabolism and tumor stemness in the treatment of breast cancer." (PMID 34052833, 2021). "The idea that ETV4 promotes glycolysis activity is further confirmed by the finding that knockdown of ETV4 suppressed glucose uptake and lactate production in human breast cancer cell lines." (PMID 34052833, 2021).
breast cancer (continued). "The GSEA results revealed that ETV4 expression was significantly correlated with glycolysis activity in breast cancer and HCC tissues." (PMID 34052833, 2021). "Taken together, these results demonstrate that ETV4 is required for CSC-like properties in breast cancer cells." (PMID 34052833, 2021). "Since we have also shown that ETV4 knockdown inhibits glycolytic gene expression, it is rational that ETV4 plays a role in maintaining breast cancer stemness." (PMID 34052833, 2021). "ETV4 loss significantly inhibits the expression of HK2, LDHA as well as other glycolytic enzymes, reduces glucose uptake and lactate release in breast cancer cells." (PMID 34052833, 2021). "Collectively, these data suggest that ETV4 facilitates maintenance of cancer stemness through regulating glycolysis in breast cancer." (PMID 34052833, 2021). "GSEA of the TCGA breast cancer dataset revealed that ETV4 expression was positively correlated with the Hedgehog signaling, one of the embryonic development-related pathways implicated in stem-cell maintenance." (PMID 34052833, 2021). "We propose that ETV4 promotes breast cancer stemness probably by altering glycolysis metabolism, as the increase in sphere formation capacity caused by ETV4 overexpression is reversed in the presence of a glycolysis inhibitor." (PMID 34052833, 2021). "Together, these data suggest that ETV4 regulate breast cancer cell stem-like traits by modulating SHH-GLI1 signaling pathway." (PMID 34052833, 2021). "ETV4 is enriched in BCSCs, its knockdown and overexpression suppresses and promotes breast cancer cell stem-like traits, respectively." (PMID 34052833, 2021). "In breast cancer, ETV4 was transcriptionally activated by the ECM via the integrin/BRAF/TAK1/ERK pathway." (PMID 34623791, 2021). "In breast cancer, ETV4 down-regulates the expression of the cyclin D2 gene and up-regulates the expression of the cyclin D3 gene to promote cell proliferation." (PMID 34736492, 2021). "In human breast cancer and hepatocellular carcinoma tissues, ETV4 expression is positively correlated with glycolytic signaling." (PMID 34052833, 2021). "The ETS transcription factor ETV4 is involved in the main steps of organogenesis and is also a significant mediator of tumorigenesis and metastasis, such as in breast cancer." (PMID 29996935, 2018). "The ETV4 transcription factor is involved in tumorigenesis and metastatic processes, particularly in breast cancer, a heterogeneous illness with different subtypes." (PMID 29996935, 2018). "We have described cyclin D2 to act as a negative regulator of the ETV4-induced responses in mammary cancer cells." (PMID 29996935, 2018). "Given that MMPs are key actors of the tumorigenic and metastatic processes, we evaluated the influence of MMP13 on phenotypic modification of mammary cancer cells and in a context of ETV4 overexpression." (PMID 29996935, 2018). "Altogether, these results show that MMP13 acts as a relay of ETV4 to control mammary cancer cells’ tumorigenic abilities." (PMID 29996935, 2018). "The effects of oncogenic Etv4 and Etv5 on these processes in a subset of target genes strengthen our understanding of their roles in breast cancer cells." (PMID 28446749, 2017). "Moreover, pharmacological inhibition of FASN in HER2-positive breast cancer cells resulted in the accumulation of ETV4/PEA3, a transcriptional repressor of the HER2 gene, and reduced HER2 transcript and protein levels." (PMID 38730603, 2024). "Zhu et al10 unraveled that ETV4 enhances glycolytic activity and stemness in breast cancer." (PMID 37553792, 2023). "ETV4 activates glycolysis to strengthen breast cancer cell stemness." (PMID 36368999, 2022). "Moreover, extracellular S100A8/A9 can regulate breast cancer aggressiveness by inducing EMT via the MCAM/ETV4 axis." (PMID 35936690, 2022).
breast cancer (continued). "Mechanistically, on the one hand, we find that ETV4 may enhance glycolysis activity to facilitate breast cancer stemness; on the other, ETV4 activates Sonic Hedgehog signaling by transcriptionally promoting CXCR4 expression." (PMID 34052833, 2021). "For example, increasing evidence shows that ETV4 is able to promote breast cancer metastasis by transcriptionally activating expression of epithelial-mesenchymal transition (EMT) inducers such as ZEB1 and SNAIL135,36, and of extracellular matrix-degrading proteinases such as MMP2 and MMP937." (PMID 34052833, 2021). "Considering the upregulated expression of ETV4 in breast cancer, targeting ETV4 may be an alternative strategy to inhibit glycolysis in breast cancer." (PMID 34052833, 2021). "Our study reveals that ETV4 can activate SHH signaling to enhance breast cancer cell stemness." (PMID 34052833, 2021). "To evaluate whether ETV4 stimulate SHH signaling activation, we knocked down ETV4 expression and found decreased protein levels of SHH and GLI1 in ETV4-silenced breast cancer cells." (PMID 34052833, 2021). "Upregulation of ETV4 in BCSCs prompted us to speculate that ETV4 is necessary for sustaining breast cancer stemness." (PMID 34052833, 2021). "Mechanistically, on the one hand, breast cancer cell stemness relies on glycolytic metabolism which may be regulated by ETV4." (PMID 34052833, 2021). "Based on these findings, it is rational to hypothesize that ETV4 facilitate SHH signaling activation by modulating CXCR4 expression in breast cancer." (PMID 34052833, 2021). "In breast cancer, the selective estrogen receptor modifier, tamoxifen, inhibits the expression of ETV4 and ETV5 messenger ribonucleic acid (mRNA), which could reduce the risk of breast cancer." (PMID 34736492, 2021). "A similar relationship was observed in breast cancer, but for ETV4 and MMP13." (PMID 33648461, 2021). "ETV4 is also required for stem-like traits in breast cancer cells." (PMID 34052833, 2021). "Moreover, besides its involvement in breast cancer cell stemness by modulating glycolytic gene expression, we show that ETV4 also activates SHH signaling to promote breast cancer stemness via transcriptionally regulating its target gene CXCR4." (PMID 34052833, 2021). "We next asked whether ETV4 promotes breast cancer cell stem-like properties by regulating glycolysis." (PMID 34052833, 2021). "We then examined the levels of CXCR4 in ETV4-dificient and -overexpressing breast cancer cells." (PMID 34052833, 2021). "Indeed, to decipher the relevance of ETV4 and MMP13 association in breast cancer, we assessed MMP13 and ETV4 mRNA expression levels in a series of 456 breast cancer samples." (PMID 29996935, 2018). "However, the cellular and molecular mechanisms regulated by the ETV4 factor during mammary cancer progression are still poorly understood." (PMID 29996935, 2018). "We also described that ETV4 overexpression in a mammary epithelial cell line confers tumorigenesis-like properties as well as an increased ability to grow and that ETV4 repression reduces tumorigenesis in mammary cancer cells." (PMID 29996935, 2018). "Importantly, the expression of MMP13 and ETV4 messenger RNA was characterized in 456 breast cancer samples." (PMID 29996935, 2018). "MMP13 potentiates the effects of the ETV4 oncogene during breast cancer genesis and progression." (PMID 29996935, 2018). "Pea3/ETV4 is highly expressed in Her/Neu expressing breast cancer cells and tissues, and the major targets for Pea3/ETV4 previously identified in these tissues were matrix metalloprotease enzymes, particularly MMP1, MMP2 and MMP9, which are required for the initiation of cell migration." (PMID 28158215, 2017). "Considering that CSCs can be highly glycolytic or oxidative phosphorylation (OXPHOS) dependent, and that ETV4 is specifically expressed in undifferentiated embryonic stem cells, we next explored whether ETV4 was involved in stem-like properties in breast cancer cells." (PMID 34052833, 2021).
breast cancer (continued). "Finally, ETV4 and MMP13 co-overexpression is associated with poor prognosis in breast cancer." (PMID 29996935, 2018). "RT-qPCR analysis confirmed high levels of ETV4 expression in BxPC3 (pancreatic cancer), MDA-MB-231 (breast cancer), RBE (intrahepatic cholangiocarcinoma), and SK-Hep1 (liver cancer) cells." (PMID 40469297, 2025). "ETV4 is also a downstream target of HER2, advancing breast cancer progression through enhanced proliferation and migration." (PMID 40536817, 2025). "Nanopore sequencing allowed quantification of ETV4 transcripts: among prostate cell lines canonical ETV4 were the most abundant transcripts in PC3 (76.1%) and RWPE (61.5%) and also in breast cancer (66.2%) and leukemic (85.2%) cell lines." (PMID 37002241, 2023). "This correlation between ETV4 and PANX1 levels also remains in breast cancer, prostate cancer, and melanoma, which further broadens the contextual implications of ETV4 for PANX1 expression." (PMID 35194046, 2022). "ETV5, a member of the subfamily of PEA3 (ETV1, ETV4, and ETV5), has a prominent role in regulating the progression of human breast cancer and thyroid cancer." (PMID 33931578, 2021). "Taken together, these results reveal that CXCR4, transcriptionally regulated by ETV4, is a mediator in ETV4-induced SHH pathway activation and stem-like traits in breast cancer cells." (PMID 34052833, 2021). "Significantly, ETV4 expression in human breast cancer and HCC samples correlates with glycolytic signaling, highlighting a possible role of ETV4 in mediating glycolytic shift in human cancers." (PMID 34052833, 2021). "Our study indicates that ETV4 expression is increased in the BCSC subpopulation and breast cancer spheres." (PMID 34052833, 2021). "ETV4 knockdown also downregulated HK2, LDHA and PDK1 protein levels in breast cancer cells." (PMID 34052833, 2021). "Notably, the effects of ETV4 knockdown on the mRNA expression of HK2 and PKM2 are different in HCC and breast cancer cells, suggesting a cancer type-specific regulation of these two enzymes by ETV4." (PMID 34052833, 2021). "However, we find that ETV4 downregulates CDKN1A in prostate cells and also in MCF7 breast cancer cell line." (PMID 32791988, 2020). "Finally, we showed that ETV4 and MMP13 co-overexpression is correlated with poor prognosis in breast cancer." (PMID 29996935, 2018). "High MMP13 and ETV4 mRNA expression levels were associated with negative ER status (P = 0.00067) and the HR−/ERBB2+ subtype (P = 0.0015), two parameters associated with breast cancer aggressiveness." (PMID 29996935, 2018). "Ectopic overexpression of ETV4 in nonmetastatic human breast cancer cells increases their invasiveness and their metastatic potential in nude mice." (PMID 29996935, 2018). "Moreover, CCAR2 also functions as a coactivator for the oncogenic TF PEA3/ETV4 and promotes ERα-negative breast cancer cell growth, tumorigenesis, and cancer progression." (PMID 37524873, 2023). "Consistently, we found that ETV4 was upregulated in breast cancer tissues according to analysis of GSE42568 dataset, and we confirmed ETV4 upregulation in the majority of cancer tissues in an independent breast cancer cohort, with 8 of 12 tumors expressing significantly higher ETV4 mRNA levels." (PMID 34052833, 2021). "In addition, transcription of Notch1 and Notch4 is activated by ETV4 in breast cancer cells, suggesting the involvement of ETV4 in stimulating Notch signaling." (PMID 34052833, 2021). "Indeed, our study suggests an important interplay of ETV4 and MMP13 in human breast cancers that could, together, be assessed for their possible signature for guiding diagnosis or therapeutics." (PMID 29996935, 2018). "We next compared ETV4 expression between stem cell subpopulations and non-stem cell subpopulations of human breast epithelial MCF10A cells and breast cancer SUM149 cells using two public datasets GSE1519243 and GSE132083." (PMID 34052833, 2021).
breast cancer (continued). "By analyzing the transcriptional data of the CSC and non-CSC subpopulations in the human breast cancer cell line SUM149 (GSE132083), we find elevated expression of majority of glycolytic enzymes and ETV4 in the CSC group." (PMID 34052833, 2021).